ENSG00000289565 (novel protein)
Gene: Protein-coding gene on chromosome 1 (145,917,714 to 145,926,741, reverse strand). Ensembl gene ENSG00000289565.
Genetic constraint (gnomAD): Missense variants: 72 observed, 144.62 expected, observed/expected ratio (o/e) 0.5, 90% interval 0.41 to 0.61. Synonymous variants: 41 observed, 46.13 expected, observed/expected ratio (o/e) 0.89, 90% interval 0.69 to 1.15.